IL6 (interleukin 6)
Diseases named in the same sentence as IL6 in open-access papers (continued):
Sharing a sentence is not in itself a finding about the gene and the disease.
Obesity (continued). "Plasma levels of adiponectin can be reduced with the increase in pro-inflammatory cytokines such as TNF-α and IL-6, present in obesity, in addition to the levels of myostatin, a myokine that can elevate the adipose tissue mass." (PMID 33807959, 2021). "Il6 KO mice are characterized by maturity onset obesity, underexpression of lipolysis- and thermogenesis-related genes, and the absence of anti-obesity effects of exercise training." (PMID 34834553, 2021). "Curcumin has been demonstrated to significantly reduce the plasma levels of TNF-α and interleukin (IL)-6 and, subsequently, improves insulin sensitivity and decreases obesity-induced insulin resistance." (PMID 33669954, 2021). "It is well known, that obesity is associated with increased circulating levels of TNF-α, IL-6, and reactive oxygen species." (PMID 33526854, 2021). "Because plasma IL-6 level is higher in subjects with obesity, metabolic disease, or insulin resistance, it is generally accepted that depletion of IL-6 improves glucose regulation." (PMID 34943061, 2021). "In T2DM, obesity and dyslipidemia bring about low-grade inflammation and factor like IL-6 and TNF-α levels were found to be strikingly increased." (PMID 34956436, 2021). "Children with obesity had a large scale of adipocytes, which promoted macrophage to accumulate and release of the proinflammatory cytokines, including IL-6, IL-1β, and TNF-α, which showed some degree of chronic inflammation." (PMID 34258058, 2021). "To further confirm the beneficial effects of IB-hASC therapy on obesity, we examined the gene expression profile of several pro-inflammatory cytokines (Il1ß, Il6, I12 and Tnfα) in both scWAT and vWAT depots of DIO mice treated with saline, W-hASCs or IB-hASCs." (PMID 34230537, 2021). "In particular, the first study found an association between adherence to a low glycaemic index diet and lower levels of CRP and IL-6 in females with obesity or overweight." (PMID 33503979, 2021). "A link between obesity and inflammation has been established, and specifically the secretion of proinflammatory adipokines such as IL-1β, IL-6, TNF-α, and MCP-1 is increased." (PMID 34356649, 2021). "A high fat diet fed to C57 mice to mimic obesity induced an upregulation in IL-6, TNFa, and Ptgs-2 gene expression from adipose tissue." (PMID 34631607, 2021). "On the one hand, IRE1α promotes the activation of an obesity-associated inhibitor of the NFκB pathway, leading to the production of typical pro-inflammatory cytokines such as TNF and IL-6 in the liver." (PMID 33897888, 2021). "We suspect that these differences in IL-6 observed in the present were related to obesity since IL6 values are about 3 times higher as reported in a previous study with rheumatoid patients." (PMID 33466578, 2021). "IL-6 is another pro-inflammatory cytokine involved in obesity-related insulin resistance, although it has a more controversial role." (PMID 33547367, 2021). "Overall, the authors suggest that, in their study, inflammation is not influencing iron metabolism in pregnancy and that perhaps a certain threshold of obesity induced IL-6 has to be reached to affect hepcidin levels." (PMID 34067098, 2021). "It has been shown that mice under high feed diet (HFD) underwent induced obesity (DIO) and insulin resistance associated with finding of plasma high levels of LPS, TNF alfa, IL1 and IL6, which are all proinflammatory markers." (PMID 33668627, 2021). "To investigate the role of IDO1 and its possible relationship with IL-6 in obesity, we induced the disease by feeding mice with a high fat diet (HFD)." (PMID 34394118, 2021). "In summary, we have found that the expression of endothelial NOX5 in mice under obesity conditions increases the production of IL-6 in the endothelium." (PMID 35052534, 2021). "Specifically, expression of IL-6 from adipose tissue is elevated in obesity, with a threefold higher expression in omental fat as opposed to subcutaneous fat." (PMID 33670215, 2021).
Obesity (continued). "Not surprisingly, substantial evidence supports both the higher circulatory levels and adipose expression of these proinflammatory cytokines (IL-6, TNFα and IL-1β) in obesity settings." (PMID 34831450, 2021). "Adipose interlerkin-6 (IL-6) appeared to be a potential shared molecule exhibiting similar upregulation by both obesity and adipocyte lipolysis." (PMID 34504646, 2021). "Obesity is associated with macrophage activation and production of pro-inflammatory cytokines including TNF-α, IL-1b, and IL-6." (PMID 34970568, 2021). "At the molecular level, obesity is associated with impaired Akt activity, enhanced NF-κB and FoxO1, and increased TNF-α and IL-6 levels, all of which are related to muscle atrophy." (PMID 35010979, 2021). "IL-6 is known as one of the critical cytokine among other immune-modulating cytokines that are dysregulated most frequently in obesity, and increased circulatory levels of IL-6 have been consistently documented in obese mice and humans." (PMID 34831450, 2021). "This IL-6 trans-signaling pathway plays major roles in a range of inflammatory conditions (e.g., rheumatic diseases, inflammatory bowel diseases, obesity), and is the target of anti-IL-6 therapies (e.g., tocilizumab)." (PMID 33912579, 2021). "Obese adipocytes upregulate the expression of pro-inflammatory factors such as TNF-α and IL-6 through the obesity-inflammation-aromatase axis, resulting in enhanced transcription of CYP19 gene encoding aromatase, thereby promoting the production of aromatase." (PMID 33842335, 2021). "Most adipokines, including leptin, tumor necrosis factor-alpha (TNF-α), interleukin 6 (IL-6), resistin, or retinol-binding protein 4 (RBP4), are augmented in the obese state and promote inflammatory reactions, leading to obesity-associated comorbidities." (PMID 34948320, 2021). "In the present study, the association between obesity indices (BMI, WC, and %BF), leptin and low‐grade inflammation (CRP, IL‐6, TNF‐α) in a Zanzibari population of individuals aged 5 years and above was investigated." (PMID 33680494, 2021). "Increased levels of IL-1β and IL-6 were detected in patients with T2D and obesity, and they promoted the inflammatory process." (PMID 33921314, 2021). "Classic IL-6 signaling in T cells plays a key role in the early stages of obesity, while trans-signals are more important later." (PMID 33579000, 2021). "Chronically elevated secretion of IL-6 from AT (i.e., IL-6 as an adipokine)—as occurs in overweight, obesity, and T2DM–adversely affects insulin sensitivity and glucose metabolism." (PMID 33670492, 2021). "Along those lines, our adolescents with obesity displayed higher levels of IL-6 as also shown before by others, arguing for a plausible causative role for the observed increase in hepcidin." (PMID 34065056, 2021). "A positive relationship between various anthropometric parameters of obesity and plasma levels of IL-6 has been described for men and postmenopausal women (estrogens are known to inhibit IL-6 secretion)." (PMID 33918997, 2021). "As well, TNF-α and IL-6 knockout mouse models have shown positive energy balance, suggesting that energy accumulation, observed in obesity, induces chronic inflammation, which in turn, promotes energy expenditure as a compensatory mechanism." (PMID 34108550, 2021). "In contrast to increased IL-6 levels in obesity described in the literature, the HFD group only showed a slight increase in hepatic expression compared to the SD group." (PMID 33317065, 2020). "In obesity, adipocytes grow, enlarge, and secrete inflammatory cytokines, such as tumor necrosis factor α, interleukin-6, and high-sensitivity C-reactive protein." (PMID 33092686, 2020). "IL-6 contributes to the maintenance of glucose homeostasis, obesity regulation, microglial function, and lactate production." (PMID 33019579, 2020). "Secretion of inflammatory cytokines (eg TNFα, IL‐6) and increased lipolysis can also occur during obesity‐related complications." (PMID 32458441, 2020).
Obesity (continued). "CCL2, CCL8 and interleukin-6 are well-studied pro-inflammatory cytokines that are chronically elevated in obesity but they have also be identified as contraction-regulated myokines that have beneficial effects after exercise when levels increase acutely." (PMID 32232327, 2020). "Among individuals with obesity, visceral fat activates adipose tissue to make large amounts of adipokines and cytokines, such as tumor necrosis factor α, interleukin (IL)-6, and IL-8." (PMID 33374470, 2020). "Among all the inflammatory cytokines, IL-6 is considered to a useful marker for obesity-induced inflammation and is secreted from Kupffer cells and HSC of the liver tissue." (PMID 32948162, 2020). "M1 macrophages release pro-inflammatory cytokines, such as IL-6, which can directly promote the migration of macrophages and further promote obesity-induced inflammation." (PMID 33298044, 2020). "Herein, data presented in our study highlight the alterations in the serum levels of TNF-α, CRP, IL-6, IL-12, sVCAM-1 and sICAM-1 with the progression of obesity among Egyptian females." (PMID 32893859, 2020). "This work demonstrates that obesity-altered ASCs, via enhanced secretion of leptin, promote IL-6 and NOTCH signaling pathways in ER+BCCs leading to radiation resistance." (PMID 32326381, 2020). "In obesity, the dysfunctional adipose tissue (AT) releases increased levels of proinflammatory adipokines such as TNFα, IL-6, and IL-1β and free fatty acids (FFAs), characterizing a chronic, low-grade inflammation." (PMID 32947825, 2020). "For instance, in obesity, macrophages secrete proinflammatory cytokines, tumour necrosis factor alpha (TNFα), and interleukin-6 (IL-6) that impairs insulin signalling." (PMID 32566678, 2020). "Both IL-6 expression and MPO activity are predictors of obesity-associated morbidities, pre-diabetes, and cardiovascular diseases." (PMID 32077465, 2020). "Many studies have shown that KD approaches had an anti-inflammatory effect by reducing inflammatory markers, including C-reactive protein, TNF-α, MCP-1, interleukin-6 (IL-6), and IL-8, which are generally higher in obesity." (PMID 32848830, 2020). "On the one hand, IL6 has been considered as a pro-inflammatory cytokine, participating in the development of coronary heart disease, obesity or diabetes." (PMID 32582685, 2020). "Studies have also indicated that inflammatory cytokines such as IL-1β, TNF-α, and IL-6 which are increased in obesity and diabetes conditions modulate insulin signaling." (PMID 33293987, 2020). "Taken together, these results implied that IL-6 accelerated senescent phenotype of BMSCs through the IL-6/STAT3 pathway, suggesting a potential mechanism for bone loss in HFD-induced obesity." (PMID 33679606, 2020). "A recent study showed that plasma IL-6 levels are closely related to obesity, microglial function, and lactate production." (PMID 33019579, 2020). "As adipocytes are a known source of pro-inflammatory cytokines, including TNF-α, IL-1, and IL-6, obesity can be seen as a chronic inflammatory condition." (PMID 32691301, 2020). "In AT during obesity and insulin resistance, IL6 exposure impairs insulin signalling by interfering with IRS phosphorylation, thus increasing adipocyte lipolysis, which promotes hepatic gluconeogenesis and insulin resistance." (PMID 32785109, 2020). "Molecular markers of obesity (e.g. IL-6, CRP, leptin, interleukin 1 beta [IL-1β]) increase the generation of myeloid-derived suppressor cells (MDSCs)." (PMID 33123173, 2020). "For example, cranberries and raspberries dampened postprandial elevations of serum IL-6 and IL-18, respectively, in adults with obesity and T2D after a HF breakfast." (PMID 32605005, 2020). "IL-6 for example is elevated both in obesity patients and in the ICU patients affected with SARS-CoV-2." (PMID 32759719, 2020).
Obesity (continued). "The clinical response to TNFα inhibitors is attenuated by obesity, an effect that is less pronounced with IL-6 inhibitors and the B-cell depletion agent rituximab." (PMID 32183053, 2020). "The role of circulating cytokines in obesity is controversial, as they are considered both damaging and protective, and cytokines such as IL-6 regulate adipose tissue macrophage polarization." (PMID 32823541, 2020). "The deletion of IL-6 in mice leads to inefficient BAT transplantation with sustained obesity and insulin resistance, and blunted FGF21 increase." (PMID 32265845, 2020). "Future studies are necessary to evaluate possible dose-dependent differences as well as effects of IL-6 administration in vivo in lean and obese subjects to specify the meaning of an obesity-induced increase of IL-6 concentration on NK cell physiology." (PMID 32231659, 2020). "IL-6 is abundantly secreted by adipocytes during obesity, and aggravates obesity-induced insulin resistance." (PMID 33329579, 2020). "Obesity is also marked with high concentrations of leptin, which is also known to trigger the production of IL-6 and TNF-α from adipose tissues and to increase the risk for viral infection." (PMID 32650509, 2020). "The elevated IL-6 was associated with increased IL-6 production from adipocytes and myeloid cells within tumors and IL-6 blockage abrogated obesity induced resistance to anti VEGF therapy at both primary and metastatic sites." (PMID 33339340, 2020). "In our study, about 90% of children with obesity and in all children with normal body weight, the concentrations of IL-6 were below the detection level." (PMID 33081030, 2020). "The inflammatory cytokines associated with pericardial fat and obesity include NOV, TNFα, IL-4, and IL-6." (PMID 33202598, 2020). "In the current study, the serum levels of TNF-α, CRP, IL-6, IL-12, sVCAM-1 and sICAM-1 were evaluated with the progression of obesity classes I–III." (PMID 32893859, 2020). "Obesity induces insulin, IGFs, leptin, IL-6, TNF-α, CCL2, and PAI-1, reduces adiponectin, and disturbs gut microbiota and bile acid homeostasis." (PMID 32486076, 2020). "Increased levels of pro-inflammatory cytokines, such as TNF-α, IL-1β, IL-6, and IL-12, were observed in the intestinal tissue of mouse models with obesity, which was consistent with the present findings." (PMID 33329010, 2020). "Some mechanisms that are triggered by obesity involve the inflammatory process, which includes the production of proinflammatory cytokines such as interleukin-6 (IL-6) and tumor necrosis factor-α (TNF-α)." (PMID 32795274, 2020). "These macrophages and other immune cells infiltrated in the adipose tissue are a source of TNF-α, IL-6, and other cytokines that links obesity with inflammation and IR." (PMID 33511131, 2020). "Adiponectin has strong inverse associations with several pro-inflammatory cytokines—namely tumour necrosis factor alpha (TNFa) and interleukin-6 (IL6), which are elevated in obesity." (PMID 32069845, 2020). "The results suggested that the underlying obesity following Western diet feeding worsened the GWI intestinal inflammation, as shown by increased levels of IL1β and IL6." (PMID 32927823, 2020). "As adipose tissue has been shown to contribute to high levels of serum IL-6, this has prompted recent studies to focus on the role of Th17 cells in obesity." (PMID 32849611, 2020). "Diverse cell types like adipocytes, ASCs, and immune cells in obesity secrete and release various proinflammatory factors including IL-6, IL-1, TNF-α, leptin, and MCP-1." (PMID 32806722, 2020). "As a pro-inflammatory cytokine, deletion of IL6 in adipocytes increases adipose macrophage infiltration and promotes obesity-induced insulin resistance." (PMID 32408016, 2020). "In obesity, the enhanced production of IL-6 and other pro-inflammatory mediators as a result of higher BMI is associated with insulin resistance and with a higher risk of T2D and coronary artery disease." (PMID 33096487, 2020).
Obesity (continued). "Interleukin-6(IL-6) concentrations are positively correlated with obesity, impaired glucose tolerance, and insulin resistance." (PMID 32825154, 2020). "Serum levels of inflammatory markers, such as C-reactive protein (CRP), tumor necrosis factor α (TNF-α), and interleukin 6 (IL-6), correlate with body mass index across the broad range of obesity." (PMID 33266499, 2020). "Generally, obesity is characterized by a low‐grade of inflammation, and IL‐6 concentrations are often mildly elevated in obesity." (PMID 33312536, 2020). "Another study showed that chemically-induced CAC is exacerbated by diet-induced obesity: in this context, IL-6 production stimulates macrophage polarization to a tumor-promoting phenotype, which prompts CAC development." (PMID 32650452, 2020). "Obesity is considered an inflammatory disease with elevated levels of some cytokines such as IL-6 and TNF." (PMID 32328497, 2020). "Alistipes is a harmful microorganism, and its abundance is positively correlated with some obesity‐related parameters, such as weight and serum TG and IL‐6 gene expression." (PMID 33312536, 2020). "These unexpected and beneficial results are called the “obesity paradox”, as adipose tissue is a potent source of pro-inflammatory cytokines such as tumor necrosis factor α (TNFα) and interleukin-6 (IL-6)." (PMID 32126127, 2020). "Adipocytes are capable of secreting pro-inflammatory cytokines, including CCL2, TNF-α, and IL-6 and their production is significantly increased in obesity." (PMID 32318345, 2020). "And consistent with reports that IL-6 exerts anti-obesity effects in rodents, IL6 −/− mice that carried the R6/2 transgene had slightly higher overall weights than their IL-6 +/+ R6/2 transgenic littermates." (PMID 32448329, 2020). "It is known that in obesity, adipose tissue represents a major source of increased circulating IL6, but the relevant adipose-tissue cell type is unclear because Il6 mRNA is expressed by adipocytes, ATMs, and other adipose-tissue cell types." (PMID 32403975, 2020). "IL-6, TNF, IL-1β and MCP-1 levels are elevated in kidneys from a diet-induced obesity rat model, associated with increased kidney fibrosis and sclerotic lesions." (PMID 32508807, 2020). "A possible link of these results to diet and high fat intake and obesity is indicated by the about 12-fold elevated testicular levels of IL6 in testes of obese rhesus monkeys (n = 3), fed with a Western Style diet." (PMID 32824411, 2020). "Obesity was associated with elevated levels of CRP13 as adipocytes synthesize and secrete interleukin-6 (IL-6) and CRP14, whereas physical activity lowered levers of CRP15." (PMID 32051482, 2020). "SLKDT intervention significantly inhibited obesity‐induced inflammation by decreasing the proinflammatory factors IL‐6, TNF‐α, IFN‐γ, and IL‐1β and increasing the anti‐inflammatory cytokines IL‐4 and IL‐10." (PMID 32884731, 2020). "Obesity-associated insulin resistance induces abnormal production of inflammatory cytokines such as tumor necrosis factor (TNF)-α and interleukin 6 (IL-6)." (PMID 31991602, 2020). "This proinflammatory state is a result of increased IL-6 from leptin and insulin resistance that takes place in obesity." (PMID 33202598, 2020). "HFD induced significant obesity in mice of both strains, while the weight gain of IL-6 KO-HFD mice was significantly lower than that of WT-HFD mice." (PMID 33679606, 2020). "In fact, IL-6 is one of the primary mediators of low-grade inflammation in obesity and both CXCL-1 as well as IL-5 have been found to be altered in prediabetes." (PMID 32210914, 2020). "In contrast, in chronic states such as obesity, IL-6 acts as a pro-inflammatory cytokine via the trans-signaling pathway." (PMID 31941015, 2020).